ENSG00000273885
Gene: Small nucleolar RNA gene on chromosome 11 (93,721,797 to 93,721,866, forward strand). Ensembl gene ENSG00000273885.
Gene Ontology:
Biological process: RNA processing
Cellular component: nucleolus
Homologues: Orthologues: rat LOC120094474 (90% identical), mouse Scarna9 (87% identical).